IAH1 (isoamyl acetate hydrolyzing esterase 1 (putative))
Description:
Probable lipase.
Tractability: PROTAC: ubiquitination databases record sites on it; its protein half-life has been measured.
Gene: Protein-coding gene on chromosome 2 (9,473,658 to 9,496,543, forward strand). Ensembl gene ENSG00000134330.
Subcellular location (Human Protein Atlas): Nucleoplasm
Gene Ontology:
Molecular function: identical protein binding; hydrolase activity, acting on ester bonds
Genetic constraint (gnomAD): Loss-of-function variants: 25 observed, 29.18 expected, observed/expected ratio (o/e) 0.86, 90% interval 0.62 to 1.2. The upper end of that interval is the gene's LOEUF score, 1.2, which puts it in group 5 of 6, group 1 being the genes least tolerant of losing a copy. Missense variants: 298 observed, 296.57 expected, observed/expected ratio (o/e) 1, 90% interval 0.91 to 1.11. Synonymous variants: 139 observed, 118.58 expected, observed/expected ratio (o/e) 1.17, 90% interval 1.02 to 1.35.
Homologues: Orthologues: chimpanzee IAH1 (100% identical), macaque IAH1 (99% identical), dog IAH1 (91% identical), mouse Iah1 (84% identical), rat Iah1 (83% identical), pig IAH1 (81% identical), guinea pig IAH1 (73% identical), rabbit IAH1 (69% identical), tropical clawed frog iah1 (60% identical), zebrafish iah1 (57% identical).
Diseases named in the same sentence as IAH1 in open-access papers:
IAH1 is named in the same sentence as 11 diseases in open-access papers, as found by Europe PMC text mining. Sharing a sentence is not in itself a finding about the gene and the disease. The quoted sentences say what the papers report.
fatty liver (2 papers, 2016 to 2020). "From the present results, we identified Iah1 and Rrm2 as candidate genes in the liver for the development of fatty liver." (PMID 27855657, 2016). "Therefore, at present, we are examining the incidence of fatty liver in Iah1-knockout mice." (PMID 27855657, 2016). "In this study, we focused on Iah1 gene as the most likely candidate gene for Fl1sa, a QTL for fatty liver on chromosome 12 identified in the high-fat diet-induced fatty liver model mouse, SMXA-5." (PMID 32407372, 2020).
hepatoma (2 papers, 2016 to 2020). "We previously reported that Iah1 overexpression in a mouse hepatoma cell line (Hepa1-6) affected gene expression of the lipid metabolism." (PMID 32407372, 2020). "To examine the effect of Iah1 on hepatic lipid metabolism, we constructed a stable cell line expressing the mouse Iah1 protein in mouse hepatoma Hepa1-6 cells." (PMID 27266874, 2016).
3-methylglutaconic aciduria type 1 (1 paper, 2022). 3-methylglutaconic aciduria (3-MGA) type I is an inborn error of leucine metabolism with a variable clinical phenotype ranging from mildly delayed speech to psychomotor retardation, coma, failure to thrive, metabolic acidosis and dystonia. "The IAH1 gene encodes an acyl esterase and is associated with neonatal inflammatory skin and bowel disease, and a disease with an inborn error of leucine metabolism (3 methylglutaconic aciduria type 1)." (PMID 35379837, 2022).
epilepsy (1 paper, 2022). A brain disorder characterized by episodes of abnormally increased neuronal discharge resulting in transient episodes of sensory or motor neurological dysfunction, or psychic dysfunction. "Many of these genes are associated with epilepsy and ictogenesis, including DPP10, DOCK8, IAH1, LRRC4C, and SLC6A5." (PMID 36506088, 2022).
esophageal cancer (1 paper, 2022). A primary or metastatic malignant neoplasm involving the esophagus. "Downregulation of the hnRNP G expression and upregulation of the FOX2 expression in esophageal cancer cells were found by silencing IAH1." (PMID 36466711, 2022). "How IAH1 affects the progression of esophageal cancer may be an emerging target for future treatment of esophageal cancer." (PMID 36466711, 2022).
metabolic syndrome (1 paper, 2016). A cluster of metabolic risk factors for CARDIOVASCULAR DISEASES and TYPE 2 DIABETES MELLITUS. "However, there are no SNPs associated with metabolic syndrome in 4 candidate genes (Iah1, Rrm2, Zfp125, and Nrcam)." (PMID 27855657, 2016).
metastasis (1 paper, 2024). The spread or migration of cancer cells from one part of the body (where they first appeared) to another. "In conclusion, an IAH1-ALK fusion gene was identified from the plasma of an SCLC patient who developed unusual intradural extramedullary spinal metastasis with myelitis." (PMID 39781173, 2024).
myelitis (1 paper, 2024). An inflammatory process affecting the spinal cord. "In our case, the relationship between the IAH1-ALK fusion gene and intradural extramedullary spinal metastases with myelitis remains uncertain, because alectinib was not effective against spinal metastases." (PMID 39781173, 2024).
Stroke (1 paper, 2024). Sudden impairment of blood flow to a part of the brain due to occlusion or rupture of an artery to the brain. "The percentage of IAH1+ microglia nodules was only numerically higher in MS compared to stroke, likely indicating that the increased expression of IAH1 is also driven by other cell types than by microglia alone." (PMID 38396116, 2024). "The percentage of HLA+ cells that were also FABP5+, DAGLB+, STARD13 or IAH1+ was similar for MS and stroke (NA)WM." (PMID 38396116, 2024). "On the protein level, microglia in the non-nodular (NA)WM rarely expressed FABP5, DAGLB, IAH1, or STARD13, and microglia nodules in MS compared to in stroke were more often FABP5+, DAGLB+, or STARD13+." (PMID 38396116, 2024).
tumor (2 papers, 2022 to 2024). "Although it was unclear whether the IAH1-ALK fusion gene was involved in tumor progression or an asymptomatic mutation, we treated the patient with alectinib, an ALK inhibitor; however, this therapy did not reduce the lesions." (PMID 39781173, 2024). "Interestingly, we detected an IAH1-ALK fusion gene (variant allele frequency 0.39%, tumor fraction 45%), which suggests ALK inhibitors were applicable to his treatment." (PMID 39781173, 2024). "However, the use of ALK inhibitors without sufficient consideration is controversial, because IAH1-ALK is a novel ALK fusion gene, and the ALK signal was negative as determined by the immunostaining of lymph node metastasis samples, suggesting primary tumor heterogeneity." (PMID 39781173, 2024).
cancer (1 paper, 2024). A tumor composed of atypical neoplastic, often pleomorphic cells that invade other tissues. "Alternatively, the IAH1-ALK fusion gene might not be associated with cancer progression." (PMID 39781173, 2024).